IGF2BP1 (insulin like growth factor 2 mRNA binding protein 1)
Diseases named in the same sentence as IGF2BP1 in open-access papers (continued):
Sharing a sentence is not in itself a finding about the gene and the disease.
neuroendocrine carcinoma (1 paper, 2022). A malignant neuroendocrine neoplasm composed of cells containing secretory granules that stain positive for NSE and chromogranin. "Here, we demonstrate that IGF2BP1 promotes proliferation of neuroendocrine cancer cells by regulating the histone-lysine N-methyltransferase Enhancer of Zeste homolog 2 (EZH2) at the post-transcriptional level." (PMID 35565249, 2022). "Moreover, pharmacological inhibition of IGF2BP1-mediated EZH2 expression led to cell cycle arrest and apoptosis induction in neuroendocrine cancer cell lines." (PMID 35565249, 2022).
pancreatic adenocarcinoma (1 paper, 2022). "In contrast, IGF2BP1 expression data for pancreatic adenocarcinomas, the most frequent pancreatic tumor-type, are available indicating that IGF2BP1 expression is overall upregulated in PDAC and associated with a significantly reduced overall survival." (PMID 35565249, 2022).
papillary thyroid carcinoma (1 paper, 2024). "For instance, LINC00641 destabilized GLI1 mRNA through interacting with RPB IGF2BP1, thereby suppressing malignant traits of papillary thyroid carcinoma cells." (PMID 39425009, 2024).
Parkinson disease (1 paper, 2025). A progressive degenerative disorder of the central nervous system characterized by loss of dopamine producing neurons in the substantia nigra and the presence of Lewy bodies in the substantia nigra and locus coeruleus. "We hypothesized that OM-MSC-derived exosomes, Lnc A2M-AS1, regulate TP53INP1-mediated mitophagy by interacting with IGF2BP1 to reduce oxidative stress and improve the condition of Parkinson’s disease." (PMID 40111649, 2025). "This study demonstrated that lncRNA A2M-AS1 reduces oxidative stress and improves Parkinson's disease by regulating TP53INP1-mediated mitophagy through interaction with IGF2BP1 by combining molecular results and results of clinical samples and animal experiments both in vivo and in vitro." (PMID 40111649, 2025).
prostate tumors (1 paper, 2020). "All mRNA m6A regulators were detected on the mRNA level in prostate tumors and normal prostates except IGF2BP1 and IGF2BP3 which were excluded from subsequent analyses." (PMID 33273988, 2020).
stomach adenocarcinoma (1 paper, 2024). "IGF2BP1 with high expression in stomach adenocarcinoma (STAD), enhanced the growth and metastasis of GC in vivo, which exerts an oncogenic role in GC through enhancing the glycolytic enzyme c-Myc." (PMID 39009956, 2024).
testicular germ cell tumor (1 paper, 2025). A germ cell tumor arising from the testis. "The Cancer Genome Atlas (TCGA) data indicated that IGF2BP1 was highly expressed in testicular germ cell tumors." (PMID 41280724, 2025).
thyroid (1 paper, 2021). "In conclusion, this indicated the potential use of IGF2BP1, but also MAGEA3, expression for discriminating ATC from other thyroid malignancies, including PDTC." (PMID 32719445, 2021).
tooth agenesis (1 paper, 2015). A tooth disease characterized by failure to develop one or more missing teeth. "The present study also found that IGF2BP1 was identified as an active upstream regulator in odontoblasts and a human GWAS showed that it is one of the loci associated with tooth agenesis." (PMID 25849153, 2015).
viral hepatitis (1 paper, 2025). An acute or chronic inflammation of the liver parenchyma caused by viruses. "Despite advances in understanding canonical m6A readers such as YTHDF1–3 and YTHDC1/2, the functions of noncanonical readers – such as IGF2BP1–3, HNRNPC, and HNRNPG remain largely unexplored in the context of viral hepatitis." (PMID 40793828, 2025).
ZIKV infection (1 paper, 2024). "Zika virus (ZIKV) infection does not significantly impact the association of IGF2BP2 with IGF2BP1, IGF2BP3, and YBX1." (PMID 39565347, 2024).
tumor (261 papers, 2011 to 2026). "IGF2BP1 is linked to immune checkpoint expression and tumor mutational burden (TMB), potentially affecting programmed cell death mechanisms through immune pathways and altering cancer cell survival and death rates." (PMID 39802639, 2025). "Together, IGF2BP1 is significantly up-regulated in human cancers and is associated with tumor progression and poor prognosis." (PMID 40584294, 2025). "To validate IGF2BP1’s association with an immune-suppressive tumor microenvironment in human HGSC, we correlated IGF2BP1 mRNA expression with immune subsets identified in our mouse scRNA-seq dataset using the C2 and C5 sub-types from two public datasets." (PMID 41444249, 2025). "This study analyzed genetic variations among RMGs in HNSC, identifying prognostic genes like IGF2BP1, strongly linked to tumor progression." (PMID 39512352, 2024). "Correlation analyses in two independent tumor cohorts showed substantial relation of IGF2BP1- and MYCN-associated gene expression." (PMID 37246217, 2023). "Located on chromosome 17 at 17q21.32, IGF2BP1 is a regulator of RNA stability and over-expression of IGF2BP1 is associated with tumor progression and poor prognosis in a variety of cancers." (PMID 36293188, 2022). "We performed a pan-cancer expression analysis of IGF2BP1–3 and found that the genes encoding these proteins were significantly upregulated in most of the tumor tissues, compared with adjacent normal tissues." (PMID 36686749, 2022). "Igf2bp1 was previously shown to bind Kras RNA and synergize with a Kras mutation, inducing the formation of large tumours." (PMID 34895045, 2022). "KRASG12V mutant/IGF2BP1 transgenic mice showed an increased tumor development linked to KRAS mRNA attachment to IGF2BP1." (PMID 36362424, 2022). "Further analysis revealed that IGF2BP1 expression was significantly correlated with immune infiltration, the expression of immune checkpoints, and tumor mutational burden (TMB) in LUAD." (PMID 35154270, 2022). "This supports the notion, that IGF2BP1 drives tumor progression primarily by stabilizing mRNAs encoding pro-oncogenic proteins, mostly factors serving roles in tumor cell proliferation and cell cycle progression." (PMID 33829040, 2021). "In a mouse model of colitis-associated cancer, following the knockdown of IGF2BP1 in stromal cells, the mice showed elevated tumor burden." (PMID 34203267, 2021). "Our analyses revealed that IGF2BP1 was up-regulated in tumor tissues and associated with reduced survival time." (PMID 33500720, 2021). "We also identified upregulation of insulin-like growth factor 2 mRNA binding protein 1 (IGF2BP1), an oncofetal protein and known target of the let-7 tumor suppressor family of miRNAs that has been implicated in various cancers." (PMID 33937369, 2021). "In recent studies, we demonstrated that inhibition of IGF2BP1-RNA association by the small molecule BTYNB impairs tumor cell growth in vitro and in xenograft mouse models." (PMID 34026620, 2021). "Despite only mild differences, these analyses support the notion that IGF2BP1 tends to stabilize transcripts encoding factors promoting tumor cell vitality in vitro." (PMID 33829040, 2021). "Significantly stable c-Myc mRNA was detected in hypoxic BT549 cells with ectopic WT c-Myc CRD rather than mutant c-Myc CRD; the loss of lncRNA KB-1980E6.3 or IGF2BP1 dramatically decreased the stability of c-Myc mRNA in hypoxic tumor cells." (PMID 33469161, 2021). "By searching these genes in PubMed, we found that miR490 and IGF2BP1 have been studied for their mechanism in or association with tumor progression." (PMID 32426332, 2020). "In agreement, the meta-analysis of 33 TCGA-provided cancer transcriptome data sets, including 9282 tumor samples, indicated that high IGF2BP1 expression is associated with reduced overall survival probability." (PMID 32761127, 2020).
tumor (continued). "The enforcement of tumor cell proliferation is further amplified by the IGF2BP1-dependent stabilization of some E2F-driven mRNAs, encoding regulators of proliferation like Ki-67." (PMID 32761127, 2020). "As a post-transcriptional regulator, IGF2BP1 regulates the expression of some mRNAs required to control tumor cell proliferation and invasion, and is associated with poor overall survival and metastasis in cancer." (PMID 31897227, 2020). "The reported inhibition of IGF2BP1-RNA association and tumor cell proliferation by BTYNB impairing suggested that IGF2BP1-driven tumorigenesis is druggable in principal." (PMID 32761127, 2020). "Statistically, low miR-150 expression and/or high IGF2BP1 protein immunoreactive score were all significantly associated with high tumor grade, presence of metastasis and recurrence, as well as poor response to chemotherapy (all P < 0.05)." (PMID 30220021, 2019). "This suggested that the IGF2BP1-dependent enhancement of SRF expression is associated with the recently reported role of IGF2BP1 in promoting tumor growth and metastasis." (PMID 30371874, 2019). "A review of the literature revealed that CDH17, CNTN-1 and IGF2BP1 were associated with tumor progression and drug resistance and were identified as potential candidates for further analysis." (PMID 31427725, 2019). "IGF2BP1 is an RNA-binding protein predominantly involving in tumor progression, and its expression is associated with poor prognosis in cancers." (PMID 31488089, 2019). "In conclusion, these findings indicate that the SRF/IGF2BP1-dependent control of gene expression in cancer is largely conserved, promotes the synthesis of factors enhancing tumor cell growth and is associated with unfavorable prognosis in three solid cancers." (PMID 30371874, 2019). "This appears to be preferentially observed for transcripts encoding oncogenic factors which are targeted by tumor-suppressive microRNAs like the let-7 family, as demonstrated for IGF2BP1." (PMID 23069990, 2013). "In agreement, we observed that IGF2BP1 knockdown results in a significantly reduced half-life of the MYC mRNA in most tumor-derived cells and accordingly is associated with severely decreased cell proliferation." (PMID 23677615, 2013). "Within the colorectal cancer microenvironment, tumor-associated macrophages may rely on modifiers such as IGF2BP1 to maintain an immunosuppressive phenotype." (PMID 41376856, 2026). "This discrepancy may reflect underlying differences in tumor biology, genetic background, treatment response, or IGF2BP1-associated signaling mechanisms between Asian and Western populations." (PMID 41210679, 2025). "Besides, our findings indicate a high expression of IGF2BP1 in tumor tissues (16 normal vs. 16 tumor, P < 0.001) and its association with poorer overall survival in TCGA CRC patients (P = 0.00147)." (PMID 40082414, 2025). "Moreover, a positive correlation of IGF2BP1 expression with a higher risk score, advanced tumor grade, shorter overall survival, and poor prognosis has also been found in uterine corpus endometrial carcinoma." (PMID 40584294, 2025). "Notably additivity or even synergy was observed already at low concentrations of both compounds, providing promising evidence that the inhibition of IGF2BP1-RNA association by BTYNB is beneficial in combined treatment aiming to impair tumor cell proliferation." (PMID 32761127, 2020). "Both CDH17 and IGF2BP1 were functionally associated with cell proliferation and tumor metastasis." (PMID 31427725, 2019). "Under the stromal knockdown of IGF2BP1 in the mouse model of colitis-associated cancer, the mice showed elevated tumor burden such as enhanced tumor initiation and progression, which is partly explained by the effects of chronic inflammatory damage caused by IGF2BP1 detection." (PMID 29954406, 2018).
tumor (continued). "Additionally, the loss of IGF2BP1 was indicated to increase tumor cell proliferation related to increased IGF-II protein levels in K562 leukemia cells and promote PARP- and caspase-3 mediated apoptosis in colorectal cancer cells." (PMID 29954406, 2018). "Consequently, demethylated LncRNA GLCC1 stabilizes the IGF2 mRNA binding protein 1 (IGF2BP1)-c-Myc complex, with downstream activation of the tumour-promoting c-Myc-associated signalling pathway translating into enhanced leukaemia aggressiveness and Ara-c chemoresistance." (PMID 38674015, 2024). "Although pre-ranked GSEA analysis for RP11-366F6.2 returned no significantly gene sets, examining the functional roles of deregulated genes (such as MAGEA4, MAGEA10, HOXD10 and IGF2BP1) in the leading edge set indicated RP11-366F6.2 might be associated with tumor invasion and metastasis." (PMID 32174965, 2020). "Previously, we demonstrated that genetic inhibition of IGF2BP1 suppresses tumor progression and metastasis of LUAD." (PMID 40629079, 2025). "Concurrently, in vivo experiments have shown that knocking down IGF2BP1 or AIFM2 can effectively suppress tumor growth and metastasis." (PMID 40386780, 2025). "IGF2BP1 inhibition was associated with a higher T cell-to-tumor cell ratio, as confirmed by flow cytometry and RNA-seq of FACS-separated tumor and immune cells." (PMID 41444249, 2025). "High expression of METTL3, METTL14, FTO, YTDHF1-2 and IGF2BP1, in gastric cancer, facilitates tumor immune evasion by maintaining the stability and expression of PD-L1 transcripts." (PMID 41228380, 2025). "Collectively, these findings provide the first evidence that IGF2BP1 inhibition enhances immune checkpoint therapy by disrupting IGF2BP1-driven uncoupling of IRF1-dependent MHC-I/PD-L1 synthesis in tumor cells." (PMID 41444249, 2025). "Increased activity of the IGF2BP1 “reader”, for instance, amplifies tumor proliferation and dampens CD8+ T-cell–mediated cytotoxicity, correlating with unfavorable patient outcomes." (PMID 41228380, 2025). ",115, 116, 117 Collectively, these studies suggest that IGF2BP1 regulates phenotypic plasticity and disrupts differentiation in tumor cells." (PMID 40584294, 2025). "These suggest the potential of applying IGF2BP1 as a marker for tumor diagnosis and prognosis prediction." (PMID 40584294, 2025). "Collectively, these studies suggest that IGF2BP1 inhibitors can inhibit the growth and development of tumors, and thus targeting IGF2BP1 is a potential anti-tumor therapeutic strategy." (PMID 40584294, 2025). "As proof-of-concept, we show that the lead candidate IGF2BP1 uncouples PD-L1 from interferon-dependent signaling to modulate the immune receptor landscape and evade T cell-mediated anti-tumor immunity." (PMID 41444249, 2025). "The heatmap illustrated significantly higher DNA methylation levels of IGF2BP1/2 in tumor tissues than in adjacent normal tissues in various tumors (BRCA, BLCA, COAD, LUAD, and PRAD)." (PMID 40088376, 2025). "In GC, IGF2BP1 is overexpressed, enhancing PD-L1 mRNA stability, which boosts PD-L1 expression and allows tumor cells to evade immune system attacks." (PMID 40356985, 2025). "By elucidating how IGF2BP1 and related oncofetal RBPs coordinate immune evasion, this work expands current concepts of tumor–immune interactions beyond transcriptional control." (PMID 41444249, 2025). "Meanwhile, LINC00659 promotes tumor cell growth by regulating the stability of frizzled class receptor 6 (FZD6) mRNA in digestive tract tumors in an IGF2BP1-dependent manner." (PMID 40584294, 2025). "Knockdown of IGF2BP1 has been shown to inhibit cell migration and invasion as well as tumor metastasis." (PMID 40629079, 2025). "IGF2BP1 is significantly up-regulated in various tumor cells and has attracted attention as a potential target gene for anti-tumor therapy." (PMID 40584294, 2025).
tumor (continued). "This interaction specifically, blocks the binding between IGF2BP1 and its target RNAs, such as Kirsten rat sarcoma viral oncogene homologue (Kras), ultimately suppressing tumorigenic properties of tumor cells." (PMID 40584294, 2025). "By positively regulating a large number of pro-oncogenic, anti-apoptotic, and chemoresistance RNAs, IGF2BP1 plays important roles in many diverse pathways that promote tumor progression." (PMID 40629079, 2025). "IGF2BP1 has been recognized for its regulatory role in these mRNAs, playing crucial functions in the proliferation and growth of both normal and tumor tissues, as well as in tumor cell adhesion, apoptosis, migration, and invasion." (PMID 40082414, 2025). "IGF2BP1 enhances the stability of PD-L1 mRNA, promoting tumor immune evasion, and can inhibit the proliferation and invasion of HCC cells." (PMID 39726589, 2024). "IGF2BP1 expression was low in both normal esophageal tissue and tumor tissue, while IGF2BP2 and IGF2BP3 expression was higher in tumor tissue than in normal esophageal tissue." (PMID 38724996, 2024). "Emerging evidence also suggests that specific m6A ‘readers’, such as IGF2BP1, can modulate the stability and translation of target mRNAs, thereby affecting tumor growth and immune escape in HCC." (PMID 39606242, 2024). "The TCGA and Clinical Proteomic Tumor Analysis Consortium (CPTAC) databases showed that IGF2BP1 expression was markedly increased in CRC samples compared with normal samples." (PMID 38084791, 2024). "Patients in the high-IGF2BP1 group exhibited poorer tumor progression and worse PFS and OS prognosis." (PMID 39512352, 2024). "To further elucidate the complete modification mechanism of METTL14-G6PD in LUAD, we silenced IGF2BP1, 2, and 3 in tumor cells using siRNA transfection." (PMID 39138186, 2024). "BTYNB strongly selectively inhibits the proliferation of IGF2BP1‐positive cells and suppresses the growth of many tumours." (PMID 38943267, 2024). "For instance, in colon stromal cells, IGF2BP1 functions as a tumor suppressor, and its deletion leads to elevated hepatocyte growth factor levels in the microenvironment." (PMID 39342091, 2024). "IGF2BP1 is highly expressed in various tumors and its overexpression correlates with tumor aggressiveness." (PMID 39426983, 2024). "Recent findings indicate that the involvement of IGF2BP1/2/3, known as m6A readers, in the regulation of RNA stability plays a crucial role in tumor initiation, progression, and evolution." (PMID 38504159, 2024). "At last, IGF2BP1 holds promise as a broad-spectrum tumor marker for early diagnosis and prognostic evaluation." (PMID 39342091, 2024). "It has been reported that BTYNB decreases the association of IGF2BP1 with MYC RNA and E2F-driven RNA while inhibiting the proliferation of several tumor cells." (PMID 39534570, 2024). "Elevated IGF2BP1 expression correlated with aggressive tumor behavior, chemotherapy resistance, and immune microenvironment alterations, indicating its central role in HNSC malignancy." (PMID 39512352, 2024). "The results indicate that except for IGF2BP1/2/3, the expression of other proteins is significantly higher in tumor tissues compared to normal tissues (all p < 0.001)." (PMID 38928396, 2024). "When we knocked down IGF2BP1, 2 and 3 in tumor cells via siRNA transfection, only siIGF2BP2 markedly decreased the G6PD mRNA and protein expression level through reducing mRNA stability." (PMID 39138186, 2024). "The current study demonstrated that the MIF - (CD74+CXCR4) ligand-receptor pair is significantly active in tumor cells with elevated IGF2BP1 expression." (PMID 39512352, 2024). "Consistent with this, overexpression of IGF2BP1 in human HCC is associated with poor survival of HCC patients and positively correlated with tumor T and N grades." (PMID 38166832, 2024). "IGF2BP1 increases the growth, survival, invasion and non‐adhesion of tumour cells in the majority of cancers, as well as their resistance to treatment." (PMID 39679845, 2024).